SLC39A11 (solute carrier family 39 member 11)
Description:
Zinc importer that regulates cytosolic zinc concentrations either via zinc influx from the extracellular compartment or efflux from intracellular organelles such as Golgi apparatus. May transport copper ions as well. The transport mechanism remains to be elucidated.
Synonyms: ZIP-11; C17orf26; ZIP11
Tractability: Antibody: UniProt places it where antibodies can reach, with medium confidence; UniProt predicts a signal peptide or a membrane-spanning region; its Gene Ontology location is reachable by antibodies, with medium confidence. PROTAC: ubiquitination databases record sites on it; its protein half-life has been measured.
Target class: Transporter
Gene: Protein-coding gene on chromosome 17 (72,645,947 to 73,092,712, reverse strand). Ensembl gene ENSG00000133195.
Subcellular location: Cell membrane; Nucleus; Cytoplasm; Golgi apparatus
Subcellular location (Human Protein Atlas): Nucleoplasm
Gene Ontology:
Molecular function: copper ion transmembrane transporter activity; zinc ion transmembrane transporter activity; metal ion transmembrane transporter activity
Biological process: zinc ion import across plasma membrane; copper ion transmembrane transport; metal ion transport; transmembrane transport
Cellular component: cytoplasm; Golgi apparatus; nucleus; plasma membrane; membrane
Genetic constraint (gnomAD): Loss-of-function variants: 31 observed, 33.55 expected, observed/expected ratio (o/e) 0.92, 90% interval 0.69 to 1.25. The upper end of that interval is the gene's LOEUF score, 1.25, which puts it in group 5 of 6, group 1 being the genes least tolerant of losing a copy. Missense variants: 386 observed, 396.35 expected, observed/expected ratio (o/e) 0.97, 90% interval 0.89 to 1.06. Synonymous variants: 140 observed, 155.14 expected, observed/expected ratio (o/e) 0.9, 90% interval 0.79 to 1.04.
Homologues: Orthologues: chimpanzee SLC39A11 (99% identical), macaque SLC39A11 (99% identical), pig SLC39A11 (93% identical), guinea pig SLC39A11 (91% identical), mouse Slc39a11 (90% identical), rat Slc39a11 (89% identical), rabbit SLC39A11 (87% identical), dog SLC39A11 (81% identical), tropical clawed frog slc39a11 (71% identical), zebrafish SLC39A11 (70% identical), Drosophila melanogaster Zip48C (56% identical), Caenorhabditis elegans zipt-11 (55% identical).
Diseases named in the same sentence as SLC39A11 in open-access papers:
SLC39A11 is named in the same sentence as 36 diseases in open-access papers, as found by Europe PMC text mining. Sharing a sentence is not in itself a finding about the gene and the disease. The quoted sentences say what the papers report.
breast carcinoma (4 papers, 2016 to 2023). "We observed a higher methylation of SLC39A11 (cg05322837) correlated with lower SLC39A11 expression levels in tumors from Black compared to that in White, implicating that differences in methylation and expression of SLC39A11 may contribute to breast cancer racial disparities." (PMID 37293596, 2023). "HOXB gene family, FOXA1, SLC39A11, and SCUBE2 were found to play well-established roles in breast cancer development, and thus were the focus on our further analysis." (PMID 37293596, 2023).
bladder cancer (2 papers, 2022 to 2025). "For example, a pan-cancer TCGA analysis found that tumor overexpression of SLC39A3, SLC39A5, and SLC39A11 was associated with better overall survival after bladder cancer diagnosis, whereas tumor overexpression of SLC39A2, SLC39A8, SLC39A9, and SLC39A14 was associated with poorer survival." (PMID 39789109, 2025).
Obesity (2 papers, 2013 to 2025). Accumulation of substantial excess body fat. "Interestingly, animal studies suggested that adipose tissue may be related to selenium storage and selenium levels are associated with obesity, which may provide further support for an association between genetic variations in SLC39A11 and circulating selenium concentrations." (PMID 23698163, 2013).
Parkinsonism (2 papers, 2024 to 2026). Characteristic neurologic anomaly resulting from degeneration of dopamine-generating cells in the substantia nigra, a region of the midbrain, characterized clinically by shaking, rigidity, slowness of movement and difficulty with walking and gait. "Second, we found no apparent accumulation of Mn—which has been shown to cause parkinsonism symptoms—in the brain in Slc39a11 knockout animals for Slc30a10 and Slc39a14 knockout animals." (PMID 39114488, 2024).
Alzheimer disease (1 paper, 2024). A progressive, neurodegenerative disease characterized by loss of function and death of nerve cells in several areas of the brain leading to loss of cognitive function such as memory and language. "SLC39A11 is involved in the transport of Zn2+ and associated with Alzheimer’s disease, and also shows AG-specific expression and has an ICR in its promoter." (PMID 38449877, 2024).
breast tumor (1 paper, 2016). "Statistical analysis of Zn transporter expression indicated that similar to what was observed in breast tumor tissues, basal-like cancer cells also had significantly higher expression of MTs and SLC39A14 and lower expression of SLC39A6, SLC39A9, and SLC39A11 (fold-change >1.5; FDR, p < 0.05)." (PMID 26728511, 2016).
clear cell carcinoma (1 paper, 2015). "Other genes significantly associated with EOC histological subtypes (p<0.05) included the UGT1A (endometrioid), SLC25A45 (mucinous), SLC39A11 (low malignant potential), and SERPINA7 (clear cell carcinoma)." (PMID 26091520, 2015).
colon cancer (1 paper, 2023). "In colon cancer, SLC39A11 expression is also upregulated, possibly in response to the increased Zn demand in cancer cells." (PMID 38259456, 2023).
lung adenocarcinoma (1 paper, 2023). A carcinoma that arises from the lung and is characterized by the presence of malignant glandular epithelial cells. "SLC39A11 is also a prognostic indicator and therapeutic target in lung adenocarcinoma." (PMID 38259456, 2023).
ovarian tumors (1 paper, 2015). "In The Cancer Genome Atlas (TCGA) data, expression of SLC39A11 was significantly higher in ovarian tumors compared to normal tissues (P = 9.99x10-8)." (PMID 26091520, 2015).
type II diabetes (1 paper, 2025). "Furthermore, type II diabetes was associated with SLC16A11, SLC30A8, SLC39A11 and MTCH2." (PMID 40355757, 2025). "In contrast, we found no literature about the role of SLC39A11 in type II diabetes." (PMID 40355757, 2025).
ulcerative colitis (1 paper, 2024). An inflammatory bowel disease involving the mucosal surface of the large intestine and rectum. "Interestingly, a previous meta-analysis found that the rs7210086 SNP in SLC39A11 was associated specifically with ulcerative colitis, which supports the notion that the SLC39A11 protein plays a functional role in the intestine." (PMID 39114488, 2024).
cancer (7 papers, 2016 to 2025). A tumor composed of atypical neoplastic, often pleomorphic cells that invade other tissues. "In addition, SLC39A11 has been associated with the occurrence and/or development of several cancers, including bladder cancer, glioma, colorectal cancer, pancreatic cancer, and lung adenocarcinoma." (PMID 39114488, 2024). "In HeLa cells, SLC39A11 was shown to be essential for regulating the cell cycle and cancer progression by maintaining nuclear Zn homeostasis." (PMID 39114488, 2024).
SLC39A11 also shares sentences with these, for which no sentence is quoted: tumor (4 papers); Zinc deficiency (4); infection (3); amyotrophic lateral sclerosis (1); asthma (1); bladder urothelial carcinoma (1); breast invasive carcinoma (1); cardiovascular disease (1); cervical cancer (1); endocervical carcinoma (1); esophageal cancer (1); gastric adenocarcinoma (1); glioma (1); immune dysfunction (1); leukemia (1); liver cancer (1); lung squamous cell carcinoma (1); major depressive disorder (1); metabolic syndrome (1); ovarian carcinoma (1); Pseudomonas aeruginosa PA14 infection (1); renal cell carcinoma (1); uterine corpus endometrial carcinoma (1).